MYC (MYC proto-oncogene, bHLH transcription factor)
Diseases named in the same sentence as MYC in open-access papers (continued):
Sharing a sentence is not in itself a finding about the gene and the disease.
lymphoma (continued). "Several studies have shown that BPTES can significantly inhibit the growth of xenograft tumors initiated with c-Myc-transformed lymphoma cells, and induce apoptosis in IMR90-ERMYC and HA1E-MYCER cells in a MYC-dependent manner." (PMID 27419628, 2016). "Encouraged by the inverse correlation of MYC with BMAL1 and CLOCK expression in U2OS cells, we assessed expression of these genes in human lymphoma by analysing RNA-seq data of 102 patient samples." (PMID 27339797, 2016). "We analyzed a short 500-bp region from the human c-MYC promoter between P0 and P1 that represents a major breakage hotspot found in c-MYC translocation-induced lymphomas and leukemia." (PMID 27532010, 2016). "MYC translocation was present in four of 26 (15%) evaluable cases, two of them had an additional BCL2 rearrangement (Double hit lymphoma) and one patient had additional BCL2 and BCL6 rearrangements (Triple hit lymphoma)." (PMID 27285986, 2016). "Patients with both MYC and BCL2 CNA had similar outcomes to those with classic double hit lymphoma or protein double expression lymphoma (MYC and BCL2/BCL6 coexpression)." (PMID 26158410, 2015). "The concurrent presence of a MYC and CCND1 rearrangement is rare, accounting for approximately 10% of the patients with double hit and triple hit lymphomas in the Mitelman database." (PMID 26517511, 2015). "FISH analyses using BAC clones covering lymphoma breakpoints (BCL2, BCL6, BCL11A, CCND1, CCND3, IG-H/K/L, JAK2, LMO2, MYC, PAX5, REL) all tested normal, excluding rearrangements at these loci." (PMID 26599546, 2015). "It was reported that MYC concurrent with BCL2 or/and BCL6 translocations in DLBCL, called double-hit lymphoma or triple-hit lymphoma (DHL/THL), determines highly aggressive clinical behavior with extremely poor outcome and resistance to chemotherapy." (PMID 26158410, 2015). "Most DH lymphomas had MYC and BCL2 gene translocations, whereas a small subset has MYC/BCL6 rearrangements." (PMID 26416427, 2015). "A proportion (21–83%) of DLBCLs with MYC translocation also harbour a BCL2 and/or BCL6 translocation, known as ‘double‐hit’ or ‘triple‐hit’ lymphoma." (PMID 27347428, 2015). "While inputting lymphoma into TMREC and ranking the results, a cascade named TP73 → miR-145 → MYC → miR-15a → MYB → miR-155 → SPI1 → miR-338 with the highest score was obtained." (PMID 25932650, 2015). "A previous study demonstrated that MYC and E2F1 drive TOPK expression in high-grade malignant lymphoma." (PMID 26450903, 2015). "A total of 54 (40 %) cases were positive for both MYC and BCL2, supporting a diagnosis of double-hit lymphoma, which is a quite high number compared to those of the literature." (PMID 26146524, 2015). "On the other hand, mouse #4 with MYC and PIM2 proto-oncogenes developed extensive lymphoma in various anatomical locations, and the cells clearly showed the phenotype of pro-B cell lymphomas as judged by CD43 and membrane IgM staining." (PMID 26606454, 2015). "MYC status is a relevant issue in DLBCL, but the impact varies amongst the subtype of lymphoma and the type of MYC alteration." (PMID 26146524, 2015). "One hundred seventy-two cases (84 %) were classified as MYC−, 17 (8 %) were MYC+/BCL2−/BCL6−, and 16 (8 %) were double/triple-hit lymphomas (i.e. MYC+/BCL2+, MYC+/BCL6+ or MYC+/BCL2+/BCL6+)." (PMID 26146524, 2015). "Many cases have non IG-MYC translocations, approximately 15% having a BCL2 translocation, sometimes also together MYC translocations (double-hit lymphomas)." (PMID 25364378, 2014). "Compared to MYC+/BCL2+DHL, BCL6+/MYC+DHL are less common, and most represent BCL2+/BCL6+/MYC+ triple-hit lymphomas." (PMID 24893165, 2014).
lymphoma (continued). "As one of the double hit lymphoma, Burkitt lymphoma cells obtain two critical uncontrolled genes: BCL2 and MYC, which make the malignant cells survive and proliferate out of control." (PMID 24895574, 2014). "As previously reported in Eμ-myc lymphoma models, tumor cells present increased levels of CHK1 phosphorylation, in turn limits MYC-induced apoptosis." (PMID 24586676, 2014). "In fact, Tregs proved to play an important role in limiting the immune response to human c-MYC, as Treg depletion with anti-CD25 antibody PC61 prior to immunization increased the survival of NHP-B-immunized animals after lymphoma challenge from 25% to 62.5%." (PMID 24130880, 2013). "We used data related to MYC and BCL6 based on availability of datasets and based on their central role as proto-oncogene B-cell leukaemias and lymphomas." (PMID 24511376, 2013). "MYC is also involved with IGH in DLBCL, TCR alpha/delta in T-acute lymphoblastic leukemia/lymphoma, and IG kappa and lambda chains in plasma cell myeloma." (PMID 23369149, 2013). "Taken together, these data identify a new BET bromodomain inhibitor-sensitive Rituximab response pathway that is controlled by a MYC and CYCLON-dependent gene regulatory circuit in lymphoma." (PMID 23828858, 2013). "This lymphoma cell line was chosen as it harbours both BCL2 and MYC gene translocations and therefore represents a good model system for the investigation of disease mechanisms in aggressive ‘double hit’ DLBCL." (PMID 23828858, 2013). "Based on our previous results showing that CYCLON can be regulated by MYC, we predicted that JQ1 would override CYCLON overexpression in lymphoma cells that showed concomitant MYC deregulation." (PMID 23828858, 2013). "MYC and CYCLON suppression was reversible and occurred in sequence, as shown by JQ1 washout experiments in the sensitive lymphoma cells (Raji, B593 and SUDHL4)." (PMID 23828858, 2013). "The difference in the expression patterns of genes between the healthy and DLBCL samples in the canine dataset highlighted important lymphoma-specific up-regulated genes including DHFR, MS4A1, MYC, POLA1, POLE, RRM1, TOP2A and TYMS." (PMID 24023754, 2013). "A comprehensive model for how the activity of these complexes is assimilated to direct MYC transcriptional activity and protein stability in different types of normal cells or in cancers, including MYC-associated human BL and mouse MYC-driven lymphomas, has not been developed." (PMID 22754359, 2012). "λ-hu-MYC mice were crossbred with OVA-transgenic mice and a cell line was established from a spontaneously developing OVA-transgenic λ-hu-MYC lymphoma (line 83OVA)." (PMID 22479645, 2012). "Crossing the E-mu-MYC transgene into mice transgenic for the B cell receptor specific for hen egg lysozyme (BCRHEL) and expressing the HEL antigen yields lymphomas that are more aggressive than primary E-mu-MYC lymphomas." (PMID 22880059, 2012). "GEP-based approaches have also been applied to identify MYC-driven subgroups of DLBCL, including the double-hit signature and molecular high-grade (MHG), both of which partially overlap with double- and triple-hit lymphomas." (PMID 40565058, 2025). "It highlights vital diagnostic tools, including CD45, B/T-cell markers, germinal center markers, and the Hans algorithm, as well as the role of FISH in identifying rearrangements of key genes MYC, BCL2, and BCL6, which are significant for recognizing double-hit and triple-hit lymphomas." (PMID 40428800, 2025). "If MYC protein levels exceed 40%, further investigation of MYC gene rearrangement is recommended to rule out transformation into high-grade lymphoma with BCL2 and MYC double rearrangement." (PMID 40881873, 2025).
lymphoma (continued). "Research has focused on the roles of MYC, BCL2, and Ki-67 proteins in lymphoma development." (PMID 40572636, 2025). "Therefore, performing FISH for MYC, BCL2, and BCL6 rearrangements is essential to differentiate DH or TH lymphomas." (PMID 40428800, 2025). "In addition to MYC gene translocations, lymphomas with BCL2 or BCL6 translocations and lymphomas with both MYC, BCL2, and BCL6 translocations are known as double-hit (DHL) or triple-hit (THL) lymphomas, respectively." (PMID 40729218, 2025). "In addition, DLBCL can be subclassified based on translocations of MYC, BCL2, and/or BCL6, defining high-grade B-cell lymphoma, also referred to as double-hit and triple-hit lymphoma." (PMID 40565058, 2025). "Mechanistically, we show that genetic inactivation of the PRPS2 isozyme, but not PRPS1, in MYC-driven lymphoma cells leads to elevated NADPH levels and reductive stress-mediated death." (PMID 39868212, 2025). "A high proliferative index represented by Ki67 positivity favored a high-grade B-cell lymphoma with MYC, BCL2, and BCL6 rearrangement, possibly a double-expressor phenotype or a triple hit lymphoma if proven by classic cytogenetics, FISH, or other molecular or genetic tests." (PMID 40027040, 2025). "Other tumor biomarkers are today commonly evaluated, including CD20, Ki-67, as well as MYC, BCL2, and BCL6, since a worst prognosis is predicted by the co-occurrence of MYC rearrangements with BCL2 and/or BCL6 rearrangements (i.e., “double-hit” and “triple-hit” lymphoma, respectively)." (PMID 38835350, 2024). "Molecular subtype (GCB vs. ABC) and the presence of MYC and BCL2 or BCL6 rearrangements (as seen in double- or triple-hit lymphomas) also significantly affect outcomes, with double-hit lymphomas typically exhibiting more aggressive behavior and poorer survival rates." (PMID 39640090, 2024). "Additionally, BI-2536 sensitive SCLC cells statistically exhibited enrichment in c-MYC and MYCN signatures from other cancer types and normal cells, including colorectal, leukemia, lymphoma, blood B cells, and fibroblasts." (PMID 39085197, 2024). "Despite the well-established role of MYC protein in tumorgenesis, no direct MYC-targeted therapeutic agent has been successfully used in the clinical setting for lymphoma." (PMID 38918775, 2024). "The co-occurrence of MYC rearrangements with BCL2 and/or BCL6 rearrangements, known previously as “double-hit” or “triple-hit” lymphomas, now known as High-Grade B-Cell Lymphoma (HGBCL), is associated with very poor prognosis and resistance to conventional treatments." (PMID 40191738, 2024). "From a practical standpoint, HGBCL, nos are a diagnosis of exclusion in which a lymphoma with intermediate or blastoid cytomorphology and starry sky pattern triggers a “high grade” workup to exclude BL, HG/LBCL-11q, and HGBCL with MYC- and BCL2- and/or BCL6-rearrangement." (PMID 37530792, 2024). "Also, chronic inflammation promotes an increase in chromosomal aberrations that enhance the activity of STAT3 and STAT5, or alterations leading to the progression of the lymphoma, such as TP3, MYC, and PTEN." (PMID 38435536, 2024). "We have found that PICH depletion limits the progression of MYC-induced lymphomas and, critically, does not have major toxic effects in non-tumoral tissues." (PMID 38253636, 2024). "However, if rearrangements are not found and only immunohistochemical (IHC) overexpression of MYC and BCL2 proteins is present, then the lymphoma is classified as double-expressor DLBCL (DEL)." (PMID 38397877, 2024). "This suggests that MYC and/or BCL2 overexpression may render lymphoma B cells more vulnerable to SpiD3 treatment." (PMID 38687198, 2024). "DLBCL with a MYC rearrangement (MYC-R) but not a BCL2 rearrangement (BCL2-R) nor a BCL6 rearrangement (BCL6-R) is termed single-hit lymphoma (SHL)." (PMID 38773392, 2024). "High-grade DLBCL with MYC and BCL2 or BCL6 translocations are classified as DH/TH lymphomas." (PMID 38687198, 2024).
lymphoma (continued). "In addition, GSK-3β was important in MYC-driven lymphomagenesis and inhibitors targeting GSK-3β played an inhibitory role in many lymphomas." (PMID 39588389, 2024). "This entity is characterized by the presence of MYC and BCL2 and/or BCL6 gene rearrangements and is referred to as HGBL-double-hit (DH)/-triple-hit (TH) and commonly referred to as double-hit (DHL) or triple-hit lymphoma (THL)." (PMID 39038016, 2024). "Not surprisingly, MYC is dysregulated in more than 50% of human malignancies of all types, although it is particularly prevalent in lymphoma and leukemia." (PMID 39766110, 2024). "Most studies agree in recognizing that patients with DH lymphoma have lower survival than other DLBCL, while results are still controversial on the prognostic role of the isolated MYC translocation or immunohistochemical overexpression alone of MYC, BCL2, and/or BCL6 (DE lymphomas)." (PMID 38534887, 2024). "Whole-genome sequencing of longitudinal tumor pairs representing transformation of follicular lymphoma to high-grade B cell lymphoma with MYC and BCL2 rearrangements (double-hit lymphoma) identified coding and noncoding genomic alterations acquired during lymphoma progression." (PMID 38049665, 2023). "Some findings have suggested that MYC protein expression can also occur via alternative nontranslocation‐based mechanisms in lymphoma lacking rearrangement of the MYC gene." (PMID 37641492, 2023). "ICC recommends to classifying BL cases expressing TdT as B-lymphoblastic leukemia/lymphomas with MYC rearrangement rather than BL." (PMID 36460764, 2023). "It has been shown that higher grade lymphoma, especially FL3b, is different from lower grade FL in its cytogenetic and immunohistochemical profile such as BCL2, BCL6, MYC and IRF4, which may contribute to the development of a different TME." (PMID 37591873, 2023). "In contrast, the sgControl as well as sgTrp53 Eμ-MYC/Cas9 lymphomas comprised a mixture of sIg negative pre-B lymphomas and sIg positive B cell lymphomas." (PMID 36894688, 2023). "In addition, DLBCLs were added of which approximately 15–30% have a MYC translocation, which together with BCL2 and/or BCL6 translocation or amplification are known as ‘double’ or ‘triple’-hit lymphomas." (PMID 36792656, 2023). "In this study, we found that the absence of BCL-W had no significant impact on MYC-driven lymphoma development in vivo." (PMID 37567974, 2023). "One piece of evidence for this concept comes from the studies of c-MYC transgenic mice that develop monoclonal lymphoma originating from a particular individual cell and not from all cells that express the transgene." (PMID 37035206, 2023). "Most importantly, this mechanism does not strictly depend on the reliance of tumor cells upon OxPhos and can be exploited to further enhance killing of MYC‐overexpressing cells by combining IACS‐010759 with other pro‐oxidant drugs, improving the therapeutic efficacy against high‐grade lymphomas." (PMID 37158102, 2023). "Given the importance of MYC in driving metabolic reprogramming in lymphoma progress, oncogenic HSP90 inhibitors could reverse the immunosuppressive effects on the lymphoma microenvironment and thus potentially improve efficacy of lymphoma immunotherapy." (PMID 36982568, 2023). "Taken together, our results suggest that MYC is predominantly responsible for IMPDH2 gene induction and that EBNA2 plays an indirect or supplemental role, at least in cases of EBV primary infections and lymphoma cell lines." (PMID 37409959, 2023). "C-MYC inhibitors are of particular interest in multiple aggressive lymphomas, and treatment of ENKTL cell lines with a small-molecule novel MYC inhibitor caused downregulation of both MYC and RUNX3 and, subsequently, apoptosis." (PMID 36900160, 2023).
lymphoma (continued). "An additional study even estimates that 28% of DLBCL associated with altered MYC expression harbor DDX3X mutations that are particularly enriched in tumors defined as single-hit lymphoma (MYC but no other rearrangements) and c-MYC cluster-amplified lymphoma." (PMID 37035206, 2023). "In addition, the chromosomal translocation of c-MYC can occur in leukemias and lymphomas, and the activity of c-MYC can also be deregulated at the level of expression and stability of c-MYC mRNA and proteins." (PMID 36979947, 2023). "This category now consists of MYC and BCL2 rearranged cases exclusively, while the MYC/BCL6 double hit lymphomas now constitute genetic subtypes of DLBCL, not otherwise specified (NOS) or of HGBL, NOS." (PMID 37190213, 2023). "The expression levels of IMPDH2 in primary lymphocytes and lymphomas are strongly correlated with those of MYC but not EBNA2." (PMID 37409959, 2023). "The prognosis was worse in patients with high CD24 expression than in those with low CD24 expression, both in double‐hit lymphoma and in the group without MYC rearrangement." (PMID 35289116, 2022). "Another limitation was that the Swedish lymphoma register does not record molecular data, e.g. cell of origin, or MYC/BCL-2/BCL-6 translocations." (PMID 35999271, 2022). "The expression of MYC was higher in double-hit lymphoma than in the other non-DHL lymphoma cell lines." (PMID 35091546, 2022). "Mice transplanted with these cells rapidly develop lymphomas expressing high BCL-2 and MYC." (PMID 35961968, 2022). "In this new classification, the lymphoma subtype of this research is named diffuse large B-cell lymphoma/high-grade B-cell lymphoma with MYC and BCL2 rearrangements, and BCL6 is no longer included." (PMID 36497332, 2022). "Also, restoration of HEVM ectodomain by soluble HVEM protein or HVEM-producing and CD19-targeted CAR-T cells were tumor-suppressive in MYC + /BCL2 + DLBCL cell lines and BCL2 overexpressing lymphoma xenograft model, respectively." (PMID 35303910, 2022). "These lymphomas commonly express pan-B-cell markers and a subset are EBV-positive and may show abnormalities of MYC." (PMID 35158997, 2022). "The original lymphoma was of germinal center B‐cell phenotype, was MYC‐negative by immunohistochemistry (IHC), and had BCL2 rearrangement (BCL2‐R) without MYC‐R by interphase fluorescence in situ hybridization (FISH)." (PMID 36051039, 2022). "Indeed, cancer cells maintain their oncogenic signaling through acetylation of their epigenome, with the aberrant expression of MYC, BCL6 and BCL11A induced by acetylation of histone H3 lysine 27 (H3K27) in lymphoma as an example." (PMID 36226054, 2022). "In a transgenic model of MYC‐driven lymphoma, tumor initiation and maintenance were hampered by the mTOR inhibitor everolimus, albeit without suppressing MYC level and activity." (PMID 36214609, 2022). "Apart from the results of the analyses of the GEPs, the expression of CD24 did not correlate with the frequency of double‐hit lymphoma (p = 0.053) or MYC rearrangement (p = 0.2)." (PMID 35289116, 2022). "Moreover, IACS‐010759 synergized not only with venetoclax to kill MYC/BCL2 DHL tumor cells in vivo and in vitro, as previously shown with tigecycline, but also with the MCL1 inhibitor S63845 against BCL2‐negative lymphoma cell lines." (PMID 36214609, 2022). "M-100 efficiently prevented lymphomagenesis, and induced apoptosis in human and murine lymphoma cells by reducing high MYC levels without harming untransformed B-cells." (PMID 36068335, 2022).